CEACAM3 (CEA cell adhesion molecule 3)
Description:
Major granulocyte receptor mediating recognition and efficient opsonin-independent phagocytosis of CEACAM-binding microorganisms, including Neissiria, Moxarella and Haemophilus species, thus playing an important role in the clearance of pathogens by the innate immune system. Responsible for RAC1 stimulation in the course of pathogen phagocytosis.
Synonyms: CD66d; CGM1; CGM1a; CEA; W264; W282
Tractability: Antibody: its Gene Ontology location is reachable by antibodies, with high confidence; UniProt predicts a signal peptide or a membrane-spanning region.
Gene: Protein-coding gene on chromosome 19 (41,796,587 to 41,811,554, forward strand). Ensembl gene ENSG00000170956.
Subcellular location: Membrane
Pathways (Reactome):
Hemostasis: Cell surface interactions at the vascular wall
Immune System: Neutrophil degranulation
Gene Ontology:
Molecular function: protein binding; protein tyrosine kinase binding
Biological process: regulation of immune system process; signal transduction
Cellular component: cell surface; plasma membrane; specific granule membrane; membrane
Genetic constraint (gnomAD): Loss-of-function variants: 28 observed, 28.24 expected, observed/expected ratio (o/e) 0.99, 90% interval 0.73 to 1.36. The upper end of that interval is the gene's LOEUF score, 1.36, which puts it in group 5 of 6, group 1 being the genes least tolerant of losing a copy. Missense variants: 289 observed, 321.4 expected, observed/expected ratio (o/e) 0.9, 90% interval 0.82 to 0.99. Synonymous variants: 134 observed, 129.66 expected, observed/expected ratio (o/e) 1.03, 90% interval 0.9 to 1.19.
Homologues: Orthologues: chimpanzee CEACAM3 (95% identical), macaque CEACAM1 (57% identical). Paralogues in human: CEACAM1 (63% identical), CEACAM5 (54% identical), CEACAM6 (53% identical), CEACAM4 (52% identical), CEACAM21 (47% identical), CEACAM8 (44% identical), CEACAM7 (40% identical), PSG8 (35% identical), PSG6 (35% identical), PSG2 (34% identical), PSG1 (33% identical), PSG11 (33% identical), and 12 more.
Diseases named in the same sentence as CEACAM3 in open-access papers:
CEACAM3 is named in the same sentence as 24 diseases in open-access papers, as found by Europe PMC text mining. Sharing a sentence is not in itself a finding about the gene and the disease. The quoted sentences say what the papers report.
colorectal cancer (2 papers, 2015 to 2021). A primary or metastatic malignant neoplasm that affects the colon or rectum. "Neither CEACAM7 nor CEACAM3 has previously been studied in IBD, although a reduction in CEACAM7 and CEACAM3 was reported in patients in stage II recurrent and non-recurrent colorectal cancer and in the post-operative phase of patients with colorectal cancer, respectively." (PMID 34394073, 2021).
COVID-19 (2 papers, 2021 to 2023). A disease caused by infection with severe acute respiratory syndrome coronavirus 2. "Of note, carcinoembryonic antigen-related cell adhesion molecule (CEACAM3) has been implicated in COVID-19 severity by regulating cell–cell communication of circulating neutrophils, and was one of two upregulated endothelial genes measured during our study." (PMID 36968839, 2023).
Crohn disease (2 papers, 2021 to 2024). A gastrointestinal disorder characterized by chronic inflammation involving all layers of the intestinal wall, noncaseating granulomas affecting the intestinal wall and regional lymph nodes, and transmural fibrosis. "Furthermore, research has shown that CEACAM3 is significantly upregulated in pediatric Crohn’s disease patients’ intestinal biopsies." (PMID 38343536, 2024). "Biopsies from patients with pediatric Crohn’s disease (CD) and adult ulcerative colitis (UC, active/inactive disease) showed a significant increase in CEACAM3, -5, -6 expression, while CEACAM5 expression was reduced in adult CD patients (active/inactive disease)." (PMID 34394073, 2021). "In our exploration of the expression of angiogenesis-related genes in Crohn’s disease patients, we found upregulation of OSM, CXCL5, CEACAM3, ISG20, and DUOXA1 genes in Crohn’s disease patients." (PMID 38343536, 2024).
asthma (1 paper, 2020). "Indirectly perturbed genes near ATF3 and EGR2 in the network include C2, SERPING1, ZG16B, and CEACAM3, all of which have been linked to immune response, asthma, or auto-immune diseases." (PMID 33095769, 2020).
breast tumors (1 paper, 2014). "Moreover, CEACAM1, as opposed to CEACAM3, acts as a tumor suppressor, shown to inhibit the growth of prostate, colon, and breast tumors." (PMID 24858421, 2014).
colitis (1 paper, 2025). Inflammation of the colon. "In addition, AIEC LF82 induced colitis in CEABAC10 transgenic mice harboring human CEACAM3, CEACAM5, CEACAM6, and CEACAM7 genes, and intraperitoneal injection of anti-CEACAM6 significantly decreased LF82 colonization." (PMID 41163391, 2025).
cystic fibrosis (1 paper, 2011). Autosomal recessive disorder caused by pathogenic variants in the CFTR gene (cystic fibrosis transmembrane conductance regulator), which encodes a chloride and bicarbonate channel expressed in epithelial cells, and follow the diagnosis criteria. "Interestingly, a recent study indicated that CEACAM6 and a regulatory element near the 3′ end of CEACAM3 are associated with disease severity in patients with cystic fibrosis." (PMID 21559399, 2011).
endometrial cancer (1 paper, 2024). Primary or metastatic malignant neoplasm involving the endometrium (mucous membrane that lines the endometrial cavity). "Since periodontitis is an inflammatory disease, and the occurrence of PCOS will increase the risk of endometrial cancer, CEACAM3 may play important roles in the development of PCOS and periodontitis, but the specific role needs to be further studied." (PMID 38167332, 2024).
gonorrhea (1 paper, 2014). A common sexually transmitted bacterial infection caused by Neisseria gonorrhoeae. "Thus, CEACAM3 activation serves as a double-edged sword, promoting the immunopathology of gonorrhea through an over-activated immune response that is meant to clear the bacteria causing the infection." (PMID 25188454, 2014). "Together, this study establishes that the role of CEACAM3 is not restricted to the direct opsonin-independent killing by neutrophils, since it also drives the vigorous inflammatory response that typifies gonorrhea." (PMID 25188454, 2014). "This CEACAM3-dependent expression of MIP-1α, MIP-2 and KC stimulates chemotaxis of uninfected neutrophils so as to augment their recruitment to the infected tissues, an effect that has the potential to contribute to both innate defense and the massive neutrophil recruitment that typifies gonorrhea." (PMID 25188454, 2014).
idiopathic pulmonary fibrosis (1 paper, 2023). Idiopathic pulmonary fibrosis (IPF) is a nonneoplastic pulmonary disease that is characterized by the formation of scar tissue within the lungs in the absence of any known cause. "Amine oxidase copper-containing 3 (AOC3), previously identified as an IF/TA-related DEG, and carcinoembryonic antigen-related cell adhesion molecule 3 (CEACAM3) expression were reportedly upregulated in PBMCs from idiopathic pulmonary fibrosis patients." (PMID 37623492, 2023).
inflammatory bowel disease (1 paper, 2024). A spectrum of small and large bowel inflammatory diseases of unknown etiology. "Carcinoembryonic antigen-related cell adhesion molecule 3 (CEACAM3) is mainly expressed in the lung, and also be reported to be localized in immune cells at the cervical stroma and inflammatory bowel diseases (IBD)." (PMID 38167332, 2024).
lupus (1 paper, 2018). "Nineteen probes for 16 lupus-relevant genes (Abca1, Apobec3, Ccr7, Ceacam3, Ets1, Foxp3, Hdac1, Ifng, Irf9, Itgam, Jhdm1d, Mmp9, Oscar, Slc4a1, Tbx21, and Tlr7) were identified from the database of male murine spleen." (PMID 30246031, 2018).
periodontitis (1 paper, 2024). An acute or chronic inflammatory process that affects the tissues that surround and support the teeth. "Through RF of the identified hub genes (ACSL5, NLRP12, CCRL2, and CEACAM3), pathways that activate the immune system were implicated in PCOS and periodontitis." (PMID 38167332, 2024). "ACSL5, NLRP12, CCRL2, and CEACAM3 were identified as hub genes and diagnostic genes in both PCOS and periodontitis." (PMID 38167332, 2024). "Additionally, the AUCs of ACSL5, NLRP12, CCRL2, and CEACAM3 in the periodontitis training dataset were 0.771, 0.819, 0.708 and 0.785, respectively, which also suggested the diagnostic values of 4 hub genes on periodontitis were strong." (PMID 38167332, 2024). "The 4 hub genes ACSL5, NLRP12, CCRL2, and CEACAM3 may be diagnostic genes for PCOS and periodontitis." (PMID 38167332, 2024). "Intersection of the candidate genes 1 and 2 yielded 4 hub genes (ACSL5, NLRP12, CCRL2, and CEACAM3) involved in both PCOS and periodontitis." (PMID 38167332, 2024). "Genes such as ACSL5, NLRP12, CCRL2, and CEACAM3 were identified as the molecular link between PCOS and periodontitis." (PMID 38167332, 2024).
puerperal sepsis (1 paper, 2023). "Since R28 does not bind CEACAM3, our data imply that CEACAM3 does not affect the role of R28 in the pathogenesis of S. pyogenes infections and puerperal sepsis." (PMID 37080973, 2023).
infection (8 papers, 2009 to 2024). The state of being infected such as from the introduction of a foreign agent such as serum, vaccine, antigenic substance or organism. "Depending upon the bacterial burden and presumably other factors, this CEACAM3-dependent response can either effectively clear the infection or contribute to the self-propagating inflammation that typifies gonococcal disease." (PMID 31681305, 2019). "Upon infection with Neisseria gonorrhoeae, CEACAM3 clustering triggers recruitment of Src-family PTKs to the bacteria-engaged receptor." (PMID 22448228, 2012). "While binding to CEACAMs on most cell types tends to facilitate infection, Opa proteins may also bind to neutrophil-expressed CEACAM3." (PMID 25188454, 2014). "To understand the implications of these effects during in vivo infection, we measured the relative contribution of neutrophil CEACAM3 on inflammation using a subcutaneous air-pouch model, which allows the effective recovery and analysis of leukocyte recruitment to an otherwise sterile site." (PMID 25188454, 2014). "Moreover, the integration of CEACAM-dependent effects determines the outcome of infection since neutrophil expression of CEACAM3 promotes inflammation and phagocytic clearance of the gonococci, effectively opposing the infection-promoting contribution of epithelial CEACAMs." (PMID 31681305, 2019). "However, it is important to consider that, in contrast to CEACAM3, neisserial binding to other human CEACAMs facilitates attachment to mucosal epithelia and suppression of both innate and adaptive immune responses, activities which are central to the establishment and persistence of infection." (PMID 25188454, 2014). "Following infection with CEACAM-binding gonococci, CEACAM3-mKate clustered at sites of bacterial engagement, but this did not result in re-distribution of GFP." (PMID 22448228, 2012). "Upon infection with non-opaque N. gonorrhoeae, neither CEACAM3-transfected cell line internalized significant amounts of bacteria." (PMID 22448228, 2012). "Although derivatives of strain MS11 failed to induce apoptosis in HeLa cells, a similar efficient response as with N242 was observed with derivative N1163 (Opa57; PorBIA) upon infection of HeLa-CEACAM1 but not in HeLa-CEACAM3." (PMID 19300516, 2009). "Taken together our data suggest that Opa protein-dependent engagement of CEACAM3 drives a cytokine response that is independent of its ability to promote bacterial phagocytosis and is not mediated by the ROS produced in response to infection." (PMID 25188454, 2014). "However, the expression of human CEACAM3/6 on these murine neutrophils allowed the extended survival of H. pylori within neutrophils, suggesting that the conventional H. pylori mouse model does not adequately mirror the human infection conditions." (PMID 39348445, 2024).
tumor (8 papers, 2014 to 2023). "Correspondence between the portal and systemic CEACAM3 levels suggests an aspecific filtration by the hepatic parenchyma and supports systemic levels as a representative index of the real spontaneous neoplastic cell shedding from the tumor." (PMID 26556959, 2015).
cancer (4 papers, 2014 to 2024). A tumor composed of atypical neoplastic, often pleomorphic cells that invade other tissues. "Additional signals included TRAPP5 and CEACAM3, the roles of which are currently being determined in cancer and GBM." (PMID 39123468, 2024). "The average values of CEACAM3 were related to the cancer size (T stage) (p = 0.034) and WHO stage (p = 0.035)." (PMID 26556959, 2015). "In this study, we have demonstrated the CEACAM3 specificity and a perioperative trend of CTCs which is coherent with the clinical/pathological considerations and with previous experimental findings in different cancer types." (PMID 26556959, 2015). "Finally, we have obtained similar data comparing the blood values of CEACAM3 and CEA in the patients grouped by the pathologic cancer stage." (PMID 26556959, 2015).
CEACAM3 also shares sentences with these, for which no sentence is quoted: B cell lymphoma (1 paper); bacterial infection (1); breast carcinoma (1); lipodystrophy (1); Obesity (1); pelvic inflammatory disease (1); ulcerative colitis (1).